GNAO1 (G protein subunit alpha o1)
Diseases named in the same sentence as GNAO1 in open-access papers (continued):
Sharing a sentence is not in itself a finding about the gene and the disease.
Encephalopathy (25 papers, 2016 to 2026). Encephalopathy is a term that means brain disease, damage, or malfunction. "One of the most recurrent pathogenic variants causing GNAO1 encephalopathy is an intronic mutation c.724-8G>A, which results in an in-frame insertion of two amino acid residues, Pro-Gln, after Thr241: Gαo[T241_N242insPQ]." (PMID 42024408, 2026). "To date, approximately 60 missense mutants in the GNAO1 gene, encoding Gαo, have been reported in patients diagnosed with GNAO1 encephalopathy." (PMID 40615045, 2025). "Further, the same amino acids mutated in GNAO1 encephalopathy can be mutated to cause other conditions." (PMID 40745211, 2025). "This repeatability brings us to predict that many new pathogenic mutations will be discovered in GNA-dependent diseases, falling on the amino acid sites equivalent to the mutations already known in e.g., GNAO1 encephalopathy." (PMID 40745211, 2025). "We have previously applied this concept to GNAO1 encephalopathy, a broad-spectrum neurological disorder caused by a dominant heterozygous mutation in GNAO1—the gene encoding the major neuronal G protein Gαo." (PMID 40277885, 2025). "Mutations that cause GNAO1 encephalopathy can be easily replicated in genetically modified and transgenic C. elegans and validated by rescuing phenotypic defects, primarily locomotion and egg-laying defects in worms." (PMID 40771566, 2025). "The simplicity of its neural circuit, coupled with its highly conserved genetic pathways, allows researchers to effectively replicate the mutations observed in human GNAO1 encephalopathy." (PMID 40771566, 2025). "Similar to our findings above, Gαo variants most frequently mutated (hotspot variants) in GNAO1 encephalopathies (G203E, R209H, and E246 G) were ineffective at increasing Rap1GAP1a activity at the PM." (PMID 40615045, 2025). "Understanding Gαo-mediated signaling pathways is especially critical given recent reports of a neurodevelopmental disorder (GNAO1 encephalopathy) associated with mutations in the Gαo-encoding gene." (PMID 40615045, 2025). "Some of the symptoms of GNAO1 encephalopathy, such as decreased mobility and seizure susceptibility, have been supported by the evaluation of GNAO1 disorder-associated mutations in mice." (PMID 40771566, 2025). "Among these, studies indicate the occurrence of more frequent G203R, R209C, or E246K mutations in GNAO1 encephalopathies." (PMID 40771566, 2025). "Missense mutations are most frequently seen in GNAO1 encephalopathies and spread throughout the Gαo coding sequence, affecting conserved residues with critical functions in the G protein." (PMID 38874642, 2024). "Neomorphic GNAO1 mutations underlying pediatric encephalopathies inform on other maladies caused by G protein–misfunctioning and other genetic diseases." (PMID 38874642, 2024). "Here, through a massive characterization of GNAO1 mutations, we uncovered a neomorphic feature shared by all Gαo encephalopathy mutants: a strong gain of interaction with Ric8A and, even more surprisingly, with Ric8B." (PMID 38874642, 2024). "Caused primarily by dominant de novo mutations in GNAO1, the gene encoding the major neuronal G protein Gαo, these encephalopathies lack efficient treatments." (PMID 38874642, 2024). "Altogether, the strength of the neomorphic Ric8B interaction provides the best predictive value for the clinical manifestations of GNAO1 encephalopathy mutations." (PMID 38874642, 2024). "In a humanized Drosophila model of GNAO1 encephalopathy, heterozygous flies carrying the G203R variant recapitulated some of the clinical features of the disease, manifesting motor dysfunction, reduced life span, and brain abnormalities." (PMID 36833246, 2023). "GNAO1 encephalopathy is a severe neurodevelopmental disorder caused by heterozygous de novo mutations in the GNAO1 gene." (PMID 37077890, 2023).
Encephalopathy (continued). "In sum, our findings further confirm that C. elegans is a valid in vivo model for understanding the molecular and cellular mechanisms underlying GNAO1 encephalopathy." (PMID 36833246, 2023). "GNAO1 encephalopathy is a severe neurological disease that manifests in infants or young children and is caused by heterozygous de novo mutations in the GNAO1 gene." (PMID 37077890, 2023). "In the present study, we analyzed the genotypes and clinical phenotypes of ten patients with GNAO1 gene variants and data from 17 previously reported GNAO1-related encephalopathy cases from China." (PMID 37705601, 2023). "We conclude that the reported genome-edited mice with the “humanized” fragment of the Gnao1 exon 6 provide a suitable model for preclinical safety studies of RNA-targeting therapeutics for the c.607G>A variant of GNAO1-associated encephalopathy." (PMID 37077890, 2023). "This multitude of ways to genetically ascribe the nature of the encephalopathy GNAO1 mutations has created a significant confusion and debate in the field." (PMID 36206333, 2022). "GNAO1 encephalopathy patients harbor one wt and one mutant allele of GNAO1; as the majority of the clinical cases described do not reveal mosaicism, the de novo mutations in GNAO1 supposedly arise in the gamete of one of the parents." (PMID 35090564, 2022). "More studies will show how applicable is the Zn2+-restorable GTPase deficiency mechanism to the other GNAO1 encephalopathy mutants." (PMID 36206333, 2022). "GNAO1 encephalopathy characterized by a wide spectrum of neurological deficiencies in pediatric patients originates from de novo heterozygous mutations in the gene encoding Gαo, the major neuronal G protein." (PMID 35090564, 2022). "The GTP uptake analysis has so far been performed for three GNAO1 encephalopathy mutants: Q52P and Q52R displayed complete loss of the GTP uptake, while R209H was reported to display a faster GTP uptake." (PMID 36206333, 2022). "Recently, a number of mutations in a related gene GNAI1, many of them identical to those in the GNAO1-encephalopathy, have been described to cause similar clinical manifestations in children." (PMID 34685729, 2021). "Of the point mutations identified within the coding region of GNAO1 in paediatric encephalopathy patients, all correspond to highly conserved residues, indicating their involvement in basic Gαo functions." (PMID 33036271, 2020). "Additionally, we demonstrate that common GNAO1 encephalopathy-associated Gαo variants cannot adopt the fully active conformation required for Gαo-GTP-dependent Rap1GAP1a engagement." (PMID 40615045, 2025). "This uncovers the totally unanticipated mechanism of disease dominance in GNAO1 encephalopathy: pathogenic Gαo variants are not only deficient, to different extents, in Gαo‐mediated signal transduction but also infringe the whole Gα‐ and GPCR‐signaling networks in neuronal cells." (PMID 40337144, 2025). "Our molecular characterization, coupled with the clinical case descriptions, unravels the molecular etiology of severe pediatric encephalopathies associated with GNAO1 mutations and offers invaluable knowledge required to tackle this disease in a personalized manner." (PMID 40337144, 2025). "The study of GNAO1 encephalopathy, a genetic disorder caused by mutations in the GNAO1 gene, encoding the Gαo subunit of G-proteins, presents significant challenges due to the complexity of G-protein-coupled receptor (GPCR) signaling pathways in the nervous system." (PMID 40771566, 2025). "Indeed, missense mutations in genes encoding other Gα subunits, often in the same amino acids as found mutated in GNAO1 encephalopathy, underlie a broad variety of genetic diseases." (PMID 38874642, 2024). "In our previous study, we hypothesized that GNAO1 encephalopathy mutations are neomorphic in nature, in the classical Muller categorization of genetic mutations." (PMID 38874642, 2024).
Encephalopathy (continued). "As oral zinc supplementation is an approved treatment for a multitude of disorders, including Wilson disease and various neurological conditions, our discovery may have identified the first causal treatment option for GNAO1 encephalopathies." (PMID 37887313, 2023). "The molecular dysfunction that we have “diagnosed” here for the three most common GNAO1 encephalopathy mutations is the constitutive GTP-binding state of the mutant Gαo proteins, resulting from a strongly increased rate of GTP uptake concomitant with a markedly reduced rate of GTP hydrolysis." (PMID 36206333, 2022). "Despite the limitations of the modeling and molecular dynamics approaches as compared to direct structural analysis, these findings suggest a common mechanism of the loss of the GTPase reaction in the three GNAO1 encephalopathy mutants as the displacement of the catalytic Gln205." (PMID 36206333, 2022). "Thus, mutations in the three most frequently affected GNAO1 encephalopathy amino acid residues lead to a strong increase in the rate of GTP uptake accompanied by a gigantic drop in the rate of GTP hydrolysis." (PMID 36206333, 2022). "In this regard, dietary zinc supplementation might be considered as a potential treatment option to improve the conditions of patients with GNAO1 encephalopathy, at least those carrying the G203R, R209C, and E246K mutations." (PMID 36206333, 2022). "The commonality of neurodevelopmental abnormalities in the two mutants, despite their distinct behavioral and clinical manifestations, highlights a common neurodevelopmental defect at the basis of the two dominant GNAO1 mutations and potentially of GNAO1 encephalopathies in general." (PMID 35090564, 2022). "Furthermore, our study finds that multiple mutants in Gαo associated with GNAO1 encephalopathy have defects in downstream effector interactions, which could underlie some of the manifestations of this disease." (PMID 40615045, 2025). "RNAi as a therapeutic approach to GNAO1 encephalopathies is an active area of research in GPCR biology." (PMID 40771566, 2025). "GNAO1 encephalopathies are a group of neglected genetic disorders primarily occurring due to de novo mutations in the Gαo protein-encoding gene." (PMID 40771566, 2025). "We have found that GNAO1 encephalopathy mutants dramatically upscale their cellular interactions with Ric8A—by far above those for Gαo wild‐type (wt)." (PMID 40337144, 2025). "Investigating Gαo function in the neurological system and creating therapeutic options for GNAO1 encephalopathy have attracted a lot of attention." (PMID 40771566, 2025). "In terms of therapeutic research, C. elegans has proven instrumental in identifying potential treatments for GNAO1 encephalopathy." (PMID 40771566, 2025). "Restoration of deficient cellular interactions, and partial rescue of the motor activities and life span in the Drosophila model of GNAO1 encephalopathy was observed upon dietary zinc supplementation." (PMID 40745211, 2025). "Currently, larger-scale clinical applications of zinc to treat GNAO1 encephalopathy are in place in Germany (ClinicalTrials.gov ID: NCT06412653) and China." (PMID 40745211, 2025). "Remarkably, a significant overlap in the amino acids mutated in these dominant conditions can be found with the sites mutated in GNAO1 and GNAI1 encephalopathies." (PMID 40745211, 2025). "While C. elegans provides a powerful model for studying GNAO1 encephalopathy, there remain significant challenges in fully elucidating the downstream pathways through which Gαo mutations exert their effects." (PMID 40771566, 2025). "GNAO1 encephalopathy typically manifests itself shortly after birth, and the patients present severe symptoms including profound intellectual disability, developmental delay, movement disorders, and intractable seizures." (PMID 40745211, 2025). "GNAO1 encephalopathy is a recently discovered disorder, and most known patients are infants with unclear prognosis." (PMID 38874642, 2024).
Encephalopathy (continued). "Accordingly, the C215Y variant, as the T241_N242insPQ (c.724–8G > A) mutant recently characterized by us, falls into the milder end of the spectrum of GNAO1 encephalopathy with adolescent/adult onset." (PMID 38874642, 2024). "As the strength of Gαo-Ric8B interactions correlates with disease severity, our study further identifies an efficient biomarker and predictor for clinical manifestations in GNAO1 encephalopathies." (PMID 38874642, 2024). "GNAO1 encephalopathy is characterized by a clinical phenotype combining distinctive motor, epileptic, and neurodevelopmental features." (PMID 36833246, 2023). "MD seemed to be the central feature of GNAO1 encephalopathy, with an earlier age of onset than previously reported." (PMID 37705601, 2023). "The molecular etiology of GNAO1 encephalopathies needs further elucidation as a prerequisite for the development of efficient therapeutic approaches." (PMID 37887313, 2023). "MD seemed to be the central feature of GNAO1 encephalopathy with high incidence (81%), and it was more difficult to control." (PMID 37705601, 2023). "Brain MRI showed no structural alterations and displayed widened extracerebral space in many patients with GNAO1 encephalopathy." (PMID 37705601, 2023). "Available models for in vitro proof-of-concept studies of RNA therapeutics for GNAO1 encephalopathy are patient-specific neurons and organoids derived from induced pluripotent stem cells." (PMID 37077890, 2023). "Considering the small sample size collected herein, further study with a larger sample of patients with GNAO1 encephalopathy will be required to confirm the observed genotype–phenotype correlations." (PMID 37705601, 2023). "In 2013, GNAO1-related encephalopathy was first reported in patients with Ohtahara syndrome and early infantile epileptic encephalopathy 17 (EIEE17; Online Mendelian Inheritance in Man 615473)." (PMID 37705601, 2023). "The two mouse models created and analyzed in our current study represent human patients at the two extremes of the GNAO1 encephalopathy clinical manifestation spectrum." (PMID 35090564, 2022). "The distorted proportion of the GTP/GDP-state residence of the GNAO1 encephalopathy mutants inferred from the biochemical experiments must have consequences at the cellular level." (PMID 36206333, 2022). "Last, we establish an animal model of GNAO1 encephalopathy and show that a dietary supplementation of Zn2+, the active component of the treatment, provides a significant rescue of the movement disorder and life-span shortening of the mutant animals." (PMID 36206333, 2022). "Our work provides insights into the molecular etiology of GNAO1 encephalopathy and defines a potential therapy for the patients." (PMID 36206333, 2022). "We describe a Drosophila model of GNAO1 encephalopathy where dietary zinc restores the motor function and longevity of the mutant flies." (PMID 36206333, 2022). "Our work thus describes important rodent models of GNAO1 encephalopathy and further highlights it as to a large extent neurodevelopmental disease." (PMID 35090564, 2022). "With the advances in genetic analysis application in clinical practice, the reported GNAO1 encephalopathy cases will continue to multiply." (PMID 36206333, 2022). "Given the neonatal lethality of GNAO1[G203R]/+ mice, we thus establish the first viable animal model of G203R encephalopathy with this Drosophila line capable of recapitulating some of the clinical manifestations of the disease." (PMID 36206333, 2022). "To seek understanding of the molecular etiology of GNAO1 encephalopathy, we focused on the most frequent pathologic Gαo mutants and first probed their basic biochemical properties: GTP uptake and hydrolysis, in comparison to the wild-type protein." (PMID 36206333, 2022). "Among the amino acids found mutated both in the GNAO1- and GNAI1-encephalopathy, the Gln52Pro mutations have been identified." (PMID 34685729, 2021).
Encephalopathy (continued). "GNAO1 (guanine nucleotide-binding protein, alpha-activating activity polypeptide O): GNAO1 encephalopathy clinically encompasses a complex neurologic phenotype associating severe and disabling hyperkinetic MD with/without EE." (PMID 33919646, 2021). "For GNAO1 encephalopathy, tetrabenazine was demonstrated to be the most effective drug for the management of involuntary movements." (PMID 33446253, 2021). "For GNAO1 encephalopathy, although tetrabenazine was demonstrated to be the most effective drug, emergency GPi-DBS was shown to be helpful for those patients with hyperkinetic exacerbations." (PMID 33446253, 2021). "This indicated a quite homogeneous and characteristic clinical course with high suspicion of GNAO1 encephalopathy." (PMID 33298085, 2020). "As the first step towards modeling GNAO1 paediatric encephalopathies in the fruit fly, we here describe the humanization of the Drosophila Gαo locus, finding the human protein fully replaces the insect one’s functions without any aberrations." (PMID 33036271, 2020). "Here, we report the in-depth phenotyping of genetically confirmed patients with GNAO1 encephalopathy, focusing on movement presentations." (PMID 33298085, 2020). "We also reported atypical and novel findings for GNAO1 encephalopathy including proven mosaicism in parents, which is important to guide genetic counselling." (PMID 33298085, 2020). "This study reported 6 cases of GNAO1 encephalopathy focusing on their movement phenotypes with their video clips." (PMID 33298085, 2020). "We reported 6 patients with GNAO1 encephalopathy showing an extremely diverse clinical spectrum on video." (PMID 33298085, 2020). "Considering the widely admitted deleterious effect of seizures on the developing brain, institution of this therapeutic modality early in the evolution of GNAO1 encephalopathy seems advisable." (PMID 27072799, 2016). "Such applications could accelerate the identification of therapeutic compounds that reverse receptor trapping or promote dissociation of Gαo mutants, offering new avenues for targeted therapies in GNAO1 encephalopathies." (PMID 41460161, 2026). "Moreover, the clinical diagnosis of GNAO1 encephalopathy is often delayed due to the overlap of symptoms with other neurological disorders, further complicating efforts to understand the full spectrum of this disease." (PMID 40771566, 2025). "GNAO1 encephalopathy has a broad phenotypic spectrum, the most common symptom being seizure." (PMID 40826482, 2025). "GNAO1 encephalopathy has a wide range of developing phenotypes." (PMID 40771566, 2025). "These different phenotypes can be collectively referred as GNAO1 encephalopathy." (PMID 40826482, 2025). "The spectrum of GNAO1 encephalopathy is wide and continually evolving." (PMID 40771566, 2025). "In terms of the clinical aspect of this disorder, there are no available approved diagnostic procedures to detect GNAO1 encephalopathy in the early stages of life." (PMID 40771566, 2025). "Therefore, here we provide an overview of past research and a perspective of future work, with the primary objective of focusing on GNAO1 encephalopathy and using the C. elegans model system to study these pathogenic variants." (PMID 40771566, 2025). "Ric8 as neomorphic interaction partners of GNAO1 encephalopathy mutants." (PMID 38874642, 2024). "Interaction of GNAO1 encephalopathy mutants with RGS19 and Gβγ." (PMID 38874642, 2024). "We analyzed clinical data of 27 cases of GNAO1-related encephalopathy in China." (PMID 37705601, 2023). "Consequently, the molecular etiology of GNAO1 encephalopathies, which appear to be driven in many cases via neomorphic mutations, needs further elucidation as a prerequisite for the development of efficient therapeutic approaches." (PMID 37887313, 2023).